DDX3X (DEAD-box helicase 3 X-linked)
Diseases named in the same sentence as DDX3X in open-access papers (continued):
Sharing a sentence is not in itself a finding about the gene and the disease.
breast carcinoma (continued). "Similarly, DDX3X reduces E-cadherin expression by upregulating the expression of an E-cadherin repressor Snail in breast cancer cell line MCF7 and several colorectal cancer cell lines." (PMID 38539466, 2024). "By endogenous coimmunoprecipitation, the investigators validated the interaction between AEP and DDX3X in several glioblastoma and breast cancer cell lines under hypoxia and nutrient deprivation, and they also revealed that DDX3X binds to AEP via its N-terminal region." (PMID 38299588, 2024). "In addition, DDX3X serves as a key checkpoint in apoptotic signaling in DNA damage-induced breast cancer cells." (PMID 37149668, 2023). "Moreover, we examined AEP and the corresponding DDX3X cleavage rates in multiple subtypes of breast cancer cell lines under conditions of hypoxia and nutrient deprivation." (PMID 37988165, 2023). "In addition, DDX3X protein expression levels were significantly higher in TNBC or basal-like breast cancer than those in other subtypes through CPTAC proteomic database (, S3C)." (PMID 37845393, 2023). "In breast cancer cells, DDX3X serves as a key checkpoint in apoptotic signaling." (PMID 37149668, 2023). "For example, in breast cancer, both DDX3X and DDX5 act as oncogenes." (PMID 35954483, 2022). "DDX3X functions as an oncogenic protein in regulating the tumorigenesis and metastasis of various cancers, such as glioma, prostate cancer, Ewing sarcoma, and breast cancer." (PMID 35892886, 2022). "In addition, DDX3X has been suggested to exhibit oncogenic function in multiple cancers, such as breast cancer and glioma." (PMID 35752837, 2022). "Our findings established a novel DDX3X‐assisted YY1‐KTN1 regulatory axis in breast cancer progression, which could lead to the development novel therapeutic targets for breast cancer." (PMID 35811688, 2022). "Interestingly, FHP01 also inhibited WNT signaling, a key tumorigenic pathway already correlated to DDX3X functions in breast cancer model cell lines." (PMID 34638314, 2021). "Importantly, our data strictly phenocopied the already reported effect of DDX3X knockdown in breast tumor cells, confirming very high potential for this gene as a specific target for breast cancer therapy." (PMID 34638314, 2021). "Therefore, based on all available data, DDX3X represents a promising potential target for pharmacological inhibition in breast cancers." (PMID 34638314, 2021). "In breast cancer, DDX3X expression is induced by HIF-1 under hypoxic conditions." (PMID 33627125, 2021). "DDX3X has been repeatedly proven to exert pro-tumorigenic effects in breast cancer." (PMID 34638314, 2021). "FHP01 may therefore represent a novel therapeutic approach with high potential as a personalized strategy for breast cancer, confirming DDX3X as a new actionable molecular target in these tumors." (PMID 34638314, 2021). "In turn, this supports the possibility of using DDX3X helicase inhibitors against breast cancer." (PMID 34638314, 2021). "Moreover, DDX3X is often overexpressed in breast cancers, and its expression is upregulated in distant breast cancer metastases, especially in the brain, with highly metastatic DDX3X protein expression correlated to a worse survival rate." (PMID 34638314, 2021). "High expression of nuclear DDX3X was also present in colorectal cancer and breast cancer." (PMID 33627125, 2021). "In addition, increased cytoplasmic DDX3X expression has been observed in breast cancer metastases, especially in triple-negative and high-grade cases." (PMID 31906196, 2019). "Specific shRNA-mediated DDX3X reduction suppresses breast cancer metastasis in vivo." (PMID 31906196, 2019). "DDX3X is a poor prognostic marker in cohorts of liver cancer, pancreatic cancer, breast cancer, and ovarian cancer, while patients of colorectal cancer, urothelial cancer, lung cancer, and gastric cancer expressing high DDX3X level associate with better outcomes." (PMID 31906196, 2019).
breast carcinoma (continued). "In breast cancer, DDX3X directly interacts with KLF4 mRNA and regulates its splicing." (PMID 31906196, 2019). "In addition, Ddx3x is suggested to affect cancer cell motility and proliferation, including lung, colon, and breast cancer." (PMID 31382975, 2019). "However, although these findings suggest a role for DDX3X in breast cancer, detailed investigations into its biological and molecular functions have not been performed." (PMID 29782654, 2018). "The role of DDX3X in breast cancer has been suggested by both in vitro and clinical studies." (PMID 29782654, 2018). "Importantly, studies in patients’ samples highlighted the oncogenic potential of DDX3X overexpression by showing it correlates with distant breast cancer metastases formation and a worse overall patient survival." (PMID 29782654, 2018). "Moreover, DDX3X depletion triggers a tumor intrinsic IFN-I response in breast cancer cells." (PMID 39759074, 2024). "Moreover, AEP and DDX3X had a significant positive correlation in breast cancer and glioma." (PMID 37988165, 2023). "Hence, it is possible that the DDX3X protein could enhance the effect of G3BP2 in breast cancer and play an oncogenic role in tumor initiation." (PMID 35954483, 2022). "Moreover, DDX3X expression in breast cancer was found to be increased by hypoxia-inducible factor 1-alpha (HIF-1α), a transcription factor that induces the transcriptional activation of DDX3X via binding to the HIF-responsive element located in the DDX3X promoter." (PMID 35954483, 2022). "Moreover, DDX3X augmented YY1‐KTN1 signaling‐promoted invasive cell growth of breast cancer." (PMID 35811688, 2022). "As our in vitro data suggest that the therapy of breast cancer, and more specifically of TNBCs, the most aggressive subtype of breast cancer, may benefit from the antitumor activity of DDX3X inhibitors, we next set up to study the efficacy of FHP01 treatment in vivo, in a TNBC mouse model." (PMID 34638314, 2021). "Notably, DDX3X has been repeatedly proven to exert pro-tumorigenic effects in breast cancer." (PMID 34638314, 2021). "DDX3X interacts with ADAR1, and the dual depletion of DDX3X and ADAR1 in breast cancer cells synergistically leads to the accumulation of dsRNA." (PMID 37662910, 2023). "DDX3X knockdown alone increased the expression of IFN-beta and IFN-stimulated genes, comparable to the effect of ADAR1 knockdown in MCF7 breast cancer cells." (PMID 35874614, 2022). "In our study, we verified the interaction between DDX3X/DDX5 and Ring1b, and confirmed the function and mechanism of these complexes in breast cancer metastasis." (PMID 33608512, 2021). "Similarly, we have recently observed that women whose breast cancers have low DDX3X gene expression had significantly better prognosis (Log-Rank test’s p-value < 0.01) than the group with high expression, thus supporting a specific prognostic role for DDX3X in these tumor types." (PMID 34638314, 2021). "Here we tested a DDX3X (DEAD box helicase) inhibitor (RK-33) and three clinically established breast cancer chemotherapeutics: gemcitabine (GEM), paclitaxel (PAC), and doxorubicin (DOX)." (PMID 33196681, 2020). "DDX3X was notably found to reduce the expression of the cell cycle repressor KLF4, indicating the oncogenic role of DDX3X in breast cancer." (PMID 31906196, 2019). "Transcriptome and cell cycle analysis upon depletion of DDX3X highlighted the role of this helicase in cellular proliferation and cell cycle progression in MCF7 breast cancer cells." (PMID 29782654, 2018). "DDX3X (DDX3), a human RNA helicase, is over expressed in multiple breast cancer cell lines and its expression levels are directly correlated to cellular aggressiveness." (PMID 26337079, 2015). "Consistent with our findings, tumors harboring upregulated DDX3X have been reported to exhibit stem-like properties and/or evidence of the EMT in melanoma, breast cancer, and leukemia." (PMID 25343452, 2014).
breast carcinoma (continued). "However, some studies indicate that DDX5, DDX21, and DDX3X exert tumor suppressor function in different cancers, such as hepatocellular carcinoma (HCC), breast cancer (BC) and colorectal cancer (CRC)." (PMID 35723050, 2022). "Our findings that up‐regulation of KLF4 mRNA upon DDX3X knockdown in both MCF7 cells and MDA‐MB 231 cells suggests that the DDX3X:KLF4 axis of cell cycle regulation could be a common feature of breast cancer cell lines." (PMID 29782654, 2018). "Taken together, our findings reveal a robust negative effect of DDX3X on the expression of KLF4 mRNA and protein and they suggest that DDX3X's biological function in MCF7 breast cancer cells is linked to its direct binding to KLF4 transcripts." (PMID 29782654, 2018). "However, another study using breast cancer patient samples found a positive correlation between DDX3X and E-cadherin without the involvement of HIF1." (PMID 38539466, 2024). "Although DDX3X predominantly localizes to the cytoplasm, which is closely related to the efficiency of N-terminal leucine-rich nuclear export signal–dependent (NES-dependent) CRM1-mediated export, nuclear DDX3X has been found to predict poor outcomes in colorectal and breast cancers." (PMID 37988165, 2023). "Thus, the interaction between DDX3X and ACTA2 in breast cancer might be related to the same mechanism and could be further explored." (PMID 35954483, 2022). "Thus, it might be hypothesized that DDX3X and DDX5 exert their tumor-promoting functions in breast cancer by enhancing the expression/activity of oncogenes and repressing oncosuppressors." (PMID 35954483, 2022). "Furthermore, the fact that DDX3X possesses a proproliferative function in breast cancer cells but not in nontumourigenic breast epithelial cells 26, highlights this RNA helicase as a potential therapeutic target in the fight against breast cancer." (PMID 29782654, 2018). "In our study, DDX3X depletion triggered NF-κB activation and type I IFN production in several breast cancer cells but did not promote the expression of NLRP3, pro-IL-1β, and pro-IL-18 (data not published)." (PMID 35874614, 2022). "Noteworthy, efficacy of FHP01 in breast cancer cellular in vitro models was comparable to RK33 and was not strictly correlated to DDX3X expression, as already shown for RK33 itself." (PMID 34638314, 2021). "Conversely, all of them showed low toxicity in in vivo models, suggesting that inhibition of DDX3X activity per se is not toxic and that drugs with improved physicochemical and pharmacodynamic characteristics might represent a promising approach for breast cancer treatment." (PMID 34638314, 2021). "An inhibitor of DDX3X helicase function, FHP01, exhibited very effective antiproliferative and tumor killing activity in vitro and in vivo against several breast cancer cells, yet showed no systemic toxicity but good bioavailability in vivo." (PMID 34638314, 2021).
viral infection (57 papers, 2010 to 2025). "In productive virus infection, DDX3X facilitates the translocation of virus proteins to the liquid droplet surface of DDX3X granules through initiating its dynamic associations with virus core proteins, which is crucial for lipogenesis and viral assembly." (PMID 36860877, 2023). "DDX3X dysfunction is associated with a wide range of diseases, including cancer, inflammation, female intellectual disability and viral infections." (PMID 36110852, 2022). "In fact, prior work has shown that TRPV4 can influence viral infection by inducing nuclear translocation of DEAD-Box Helicase 3 X-Linked (DDX3X), a protein that promotes nuclear viral export and translation." (PMID 35396513, 2022). "We confirmed variants with putative driver role of MAP10, MPZL1, RPS6KA1, SETD1B, TAOK2, TMEM127, and TNFRSF1A genes, and of genes linked to viral infections (DDX3X and RSF1) and DNA repair (PAXIP1)." (PMID 32321919, 2020). "Recently, the human DEAD-box RNA helicase 3 X-linked (DDX3X), involved in cancer proliferation and viral infections, has been identified as one of CK1ε substrates and its positive regulator in the Wnt/β-catenin network." (PMID 32899434, 2020). "Taken together, our results led to the identification of a new family of DDX3X inhibitors that can be used as a starting point to identify novel preclinical candidates to treat viral diseases that are caused by DDX3X dependent pathogens." (PMID 31690062, 2019). "Antibody against Flag was used to precipitate JEV-encoded NS1, and Western blot results demonstrated that Flag-tagged DDX3X could co-immunoprecipitate with JEV-encoded NS1 during virus infection." (PMID 40231822, 2025). "Seven of these acetylated proteins, including DDX3X, PTBD, TRIM56, IPO7, PPID, SHMT2, and ZC3HAV1, have been implicated in innate immunity and viral infection, based on functional annotation using databases such as GO Biological Process, KEGG and reactome." (PMID 39747662, 2025). "DDX3X has been shown to be a pro-viral factor in many cases of viral infection by promoting cap-independent translation." (PMID 38539466, 2024). "It is important to note that only the N-terminus of DDX3X is crucial for its ability to resist virus infection, which indicates that DDX3X has many critical functions in the biology of several viruses, which requires further investigation." (PMID 39155369, 2024). "Despite its complex roles in viral infections, antiviral inhibitors targeting the helicase activity of DDX3X have been developed." (PMID 39212449, 2024). "RK-33 also inhibits DDX3X during viral infections, presenting as a potential target for antiviral therapy." (PMID 38539466, 2024). "DDX3X influences innate immunity, cancer, and viral infection, aiding in the replication of viruses such as herpes simplex virus, HCV, influenza A (IAV), Japanese encephalitis virus (JEV), human immunodeficiency virus (HIV), and arenavirus (110, –, 115)." (PMID 39212449, 2024). "In many viral infections, DDX3X supports viral translation in a cap-independent manner, usually via IRES-mediated translation." (PMID 36393867, 2022). "The prion-like conformational switch of MAVS on the mitochondrial membrane is the lynchpin that propagates antiviral signaling cascades that can inhibit viral infections and is mediated by DDX3X." (PMID 35897696, 2022). "It was reported that DDX3X during viral infection can regulate the production of interferon type-1 and of interferon-stimulated genes, including ISG15." (PMID 35954483, 2022). "In Vero E6 cells infected by SARS-CoV-2, mass spectrometry analysis revealed DDX3X localizes with viral RNA foci in cytoplasm, and enhances viral infection via interactions with N protein." (PMID 35897696, 2022). "DDX3X reportedly participates in RNA metabolism, cell apoptosis, cell cycle and innate immunity in various diseases, including cancer, virus infection and inflammation." (PMID 35692100, 2022).
viral infection (continued). "DDX3X is also an important host factor in many different viral infections, where it can have pro-or anti-viral effects depending on the specific virus." (PMID 36393867, 2022). "Viral infection is a disease context in which DDX3X-mediated translation regulation plays a substantial role." (PMID 36393867, 2022). "It is worth noting that the reduction in DDX3X expression is closely related to virus infection in lung cancer and HCC." (PMID 33627125, 2021). "There are many factors that influence the expression or functions of DDX3X, including viral infection, sex and cellular localization." (PMID 33627125, 2021). "DDX3X possesses numerous functions in the processes of RNA metabolism, viral infection and cancer biology." (PMID 33627125, 2021). "Consistent with the antiviral properties of REN derivatives and of agents targeting DDX3X, our virus infection studies reveal here for the first time that the DDX3X-targeting REN derivative RK-33 also has antiviral properties." (PMID 31936642, 2020). "The activation of TRPV4 by viral proteins links viral infection to the nuclear translocation of DDX3X, where it participates in the nuclear export of unspliced or partially spliced viral RNAs8." (PMID 29899501, 2018). "Viral infection triggers host innate immune responses characterized by increased expression of interferon β and other cytokines, a process in which DDX3X also participates." (PMID 29899501, 2018). "The role of DDX3X in viral infection is complex and multifaceted." (PMID 41323147, 2025). "DDX3X is also involved in innate immunity, viral infection, and tumorigenesis." (PMID 40005552, 2025). "Recently, DDX3X was reported to exhibit significant, albeit ambiguous roles, in viral infection." (PMID 39759074, 2024). "DDX3X also participates in the formation of cytoplasmic stress granules, membraneless cytosolic bodies that form during the cell stress response, as well as during viral infection." (PMID 36110852, 2022). "Since DDX3X can directly or indirectly affects virus replication, it might participate in the progression of viral infection to oncogenesis." (PMID 33627125, 2021). "Since DDX3X plays a role in the replication of various viruses, we set out here for the first time to confirm RK-33′s ability to bind directly to DDX3X, inhibit its enzymatic activities, and test its ability to inhibit a range of viral infections." (PMID 31936642, 2020). "Finally, using NanoString RNA profiling we show the nucleocytoplasmic trafficking of DDX3X is critically important in regulating gene induction during viral infection, with marked differences in the ISG subset activated." (PMID 31575075, 2019). "Overall, these data highlight that nucleocytoplasmic trafficking of DDX3X is critically important in regulating gene induction during viral infection, with elevated nuclear expression of DDX3X impacting the resting state transcriptome as well as that in response to viral infection." (PMID 31575075, 2019). "Notably the magnitude of DDX3X relocalization between poly(I:C) stimulation and virus infection was identical (~2-fold), suggesting a specific response to invasive RNA." (PMID 31575075, 2019). "DDX3X is involved in the innate immune response against viral infections in mammalian cells." (PMID 31057547, 2019). "The role of DDX3X in viral infections is poorly characterized." (PMID 29387631, 2017). "Previous studies had explored the vital role of DDX3X in transcription regulation in the nucleus to translation initiation and stress granule formation, and found that DDX3X played a crucial role in innate immunity, as well as tumorigenesis and viral infections." (PMID 37142295, 2023). "Besides the general roles in the RNA metabolism shared with other DEAD-box proteins, DDX3X has gained particular attention due to its role in viral infections and in the maintenance of genomic stability by playing an active role in the response and repair of DNA damages." (PMID 35954483, 2022).